TLR4 (toll like receptor 4)
Diseases named in the same sentence as TLR4 in open-access papers (continued):
Sharing a sentence is not in itself a finding about the gene and the disease.
colon carcinoma (continued). "Zhou and colleagues also reported a mutual regulation of TLR4-PAR2 expression in that LPS/TLR4 stimulation increases PAR2 expression on human colon cancer SW620 cells and a PAR2 agonist induces TLR4 mRNA." (PMID 24215724, 2013). "Taken together, these results demonstrate that Nox enzymes are the most likely intra-cellular source of ROS following TLR4 signalling in colon cancer cells." (PMID 23071493, 2012). "Our data corroborate the concept that inflammation correlates with the degree of malignancy in colon cancer and provides innovative data on the role of signaling by TLR-4 both in the tumor and the microenvironment." (PMID 21059221, 2010). "Blocking TLR4 signalling in colon cancer cells resulted in the reduction of tumour growth in a subcutaneously implanted mouse model." (PMID 20145615, 2010). "In those patients with a diagnosis of pT3 (33 cases) colon cancer, those with very high levels of TLR-4 in the tumor stroma relapsed significantly earlier than those with lower expression levels." (PMID 21059221, 2010). "TLR2, TLR3, and TLR4 are overexpressed in most colon cancer cells." (PMID 40143078, 2025). "Another study proposed that mechanisms of quercetin in treating colon cancer may involve inhibition of the TLR4/NF-κB signaling pathway as well as the reduction in the production of inflammation factors, including TNF-α, Cox-2, and IL-6." (PMID 38243957, 2025). "Asparagus polysaccharide induces apoptosis of MDSCs isolated from the spleens of colon cancer mice in a toll-like receptor 4 (TLR4)-dependent manner, after treatment with asparagus polysaccharide for 48 h, the percentage of viable cells decreased from 92.7 in the control samples to 79.8 %." (PMID 39262952, 2024). "Additionally, autophagy modulated by F. nucleatum is proven to confer 5-FU chemoresistance of colon cancer cells via targeting the toll-like receptor-4 (TLR4) pathway." (PMID 37946397, 2024). "Additionally, understanding the role of TLR4 in colon cancer progression opens new avenues for therapeutic interventions." (PMID 39026223, 2024). "Importantly, pre‐treatment of mice with intraperitoneally injected TAK‐242 to block TLR4 attenuated macrophage polarisation suggesting that polarisation occurs in a TLR4‐dependent mechanism within colonic tumours." (PMID 39674881, 2024). "In addition, studies have shown that TLR4 has the potential to become a marker for disease progression in patients with colon cancer, and its low expression is correlated with a better prognosis." (PMID 39026223, 2024). "B. stercoris is able to produce acetic acid and lactic acid, and promote antitumor immunity, while the later could attenuate toll-like receptor 4 signaling and thus blocks colon tumor formation." (PMID 36992683, 2023). "P. distasonis could suppress the production of proinflammatory cytokines in a colon cancer cell line and exhibited anti-inflammatory and antitumor properties through downregulation of TLR4/MYD88/Akt signaling and stimulation of apoptosis." (PMID 37655344, 2023). "Furthermore, in AOM-treated mice under a high-fat diet P. distasonis attenuated toll-like receptor 4 signaling and Akt (protein Kinase B) activation and thereby blocked colonic tumor formation." (PMID 37255660, 2023). "Although we have confirmed that aspirin can reduce the stemness of colon cancer cells by inhibiting the expression of TLR4, thus improving the chemosensitivity of colon cancer cells, the potential molecular mechanism by which TLR4 is reduced remains unclear." (PMID 36647071, 2023). "Overexpression of TLR4 indicates progression and poor prognosis in colon cancer." (PMID 35902970, 2022). "Remarkably, depletion of Tlr4 could also significantly inhibit colon tumor numbers, volumes, and diameters induced by miR-148a deletion." (PMID 34914638, 2022). "Moreover, apple pectins had an anti-inflammatory effect in colon cancer cells, possibly via the interaction with TLR4." (PMID 35745651, 2022).
colon carcinoma (continued). "Moreover, modified apple polysaccharide was shown to suppress TLR4 expression and thus the TLR4-signalling pathway in colon cancer cells." (PMID 35745651, 2022). "Indeed, TLR4 was reported to promote immune escape of human colon cancer cells by inducing immunosuppressive factors as well as apoptosis resistance." (PMID 34026821, 2021). "Moreover, TLR4 has also been shown to promote metastasis in non-small cell lung cancer, hepatocellular carcinoma, oral squamous cell carcinoma, BC, and colon cancer." (PMID 34645466, 2021). "Additionally, it has been demonstrated that inhibition of TLR4 expression by rapamycin blocks TLR4/NF-κB signaling and promotes apoptosis of colon cancer." (PMID 32158615, 2020). "Increased TLR4 expression in the stromal compartment was associated with a significantly increased risk of disease progression, and significant tumor relapse occurred earlier in colon cancer patients with very high levels of TLR4 than in those with lower expression levels." (PMID 33299138, 2020). "Mechanisms by which F. nucleatum promotes tumor progression include generating a proinflammatory tumor-promoting microenvironment and accelerating proliferation of colon cancer cells through activation of Wnt/beta-catenin signaling and through TLR4-activated signaling to NF-κB." (PMID 32850497, 2020). "However, the expression level of TLR2 or TLR4 is only slightly increased in colon cancer samples according to the GENT2 database." (PMID 32050430, 2020). "Moreover, both innate immune cells and colon cancer cells exhibit expression of TLR4 and NLRP3 inflammatory bodies." (PMID 31754923, 2019). "Additionally, aspirin treatment leads to the downregulation of TLR4 on colon cancer cells which resulted in the decrease of colon cancer cells migration and EMT that induced by LPS." (PMID 29308184, 2018). "Another in vitro study indeed has demonstrated that RAGE but not TLR4 associates with Mrp8/14 in colon tumor cells." (PMID 30180864, 2018). "The results of our study indicate that LPS origin from intestinal flora may promote the metastasis of colon cancer to liver and aspirin may inhibit the metastasis of colon cancer by inhibiting the expression of TLR4." (PMID 29308184, 2018). "In agreement with the findings from the study, Aspirin might act as an inhibitor in the LPS-induced metastasis of colon cancer and TLR4 could be used as a prognostic marker and a potential therapeutic target." (PMID 29942487, 2018). "Statins have also been shown to inhibit LPS-induced EMT via the downregulation of TLR4 and NFkB in human biliary epithelial cells, and could be an additional agent for reducing the metastatic potential of colon cancer cells." (PMID 29942487, 2018). "Our work have demonstrated that activation of NF-κB signaling pathway was participated in the LPS-induced EMT and the invasive potential of colon cancer cells is in a TLR4 dependent manner and that aspirin inhibited the EMT and metastasis by down-regulating the NF-κB signaling pathway." (PMID 29308184, 2018). "Collectively, our results indicate that Fn may primarily activate β-catenin signaling through its LPS, subsequently involving a TLR4/PAK1 cascade in colon cancer cells." (PMID 28423670, 2017). "Inflammation-induced colon cancer was prevented by the genetic ablation of Tlr4 in mice." (PMID 29228570, 2017). "Given the higher frequency of the TLR4 G allele in CRC patients compared to healthy controls, clear evidence is presented for a novel association between TLR4rs10759931polymorphism and susceptibility to colon cancer development in the Saudi Arabian population." (PMID 26771524, 2016). "Moreover, our analysis also demonstrated that TLR4 expression is significantly increased in colon tumor tissues compared with matching normal colon tissues." (PMID 26771524, 2016). "Our data suggest that TLR4 SNPs could possibly serve as biomarkers for decision making in colon cancer treatment." (PMID 26771524, 2016).
colon carcinoma (continued). "This is due to overexpression of TLR4 activity in colon cancer patients." (PMID 26771524, 2016). "Targetting the LPS/TLR4/NF-κB signaling pathway with inhibitors may hold promises in treating colon cancer." (PMID 27679575, 2016). "In this study, we demonstrated that the TLR-4 agonist Rv2299c could be used as a potential adjuvant with TA-loaded DC in a colon cancer vaccine." (PMID 26418952, 2015). "We and others have described a role for TLR4, the receptor for LPS, in colon cancer." (PMID 24887394, 2014). "In animals with colonic tumors, treatment with an anti-TLR4 antibody results in smaller tumors." (PMID 24887394, 2014). "The association between survival and TLR4 expression was corroborated by a strong correlation between TLR4 expression (Short and Long2) and DFS among 290 colon cancer patients ranging from Duke’s stages A through D (exp (coef) 0.78, p = 0.0008 and exp (coef) 1.47, p = 0.0006) (GSE14333)." (PMID 24887394, 2014). "Interestingly, although engagement of TLR3 expressed in human breast tumor cells induces massive apoptosis, triggering TLR4 in murine colon cancer MC26 cell line leads to immune evasion mediated by the inhibition of T- and NK-cell activities." (PMID 24155891, 2013). "The goal of our study was to determine whether TLR4 played a role as a tumor promoter in sporadic colon cancer." (PMID 23691015, 2013). "In preclinical models, we and others have shown that blocking TLR4 could prevent colonic tumor development or reduce metastatic tumor burden." (PMID 23691015, 2013). "To explore how TLR4 might participate in colonic tumor development, we took a multifaceted approach." (PMID 23691015, 2013). "As colon cancer cells express Nox enzymes and Toll-like receptor 4 (TLR-4), we hypothesised that LPS may potentiate the ability of colon cancer cells to metastasise via Nox enzyme mediated redox signalling." (PMID 23071493, 2012). "Changes induced by unbalanced inflammation and bacteria could contribute to colon cancer development through release of LPS that binds TLR-4 present on the surface of inflammatory cells, and induce an inflammatory reaction." (PMID 21059221, 2010). "Rapamycin may abrogate TLR-triggered colon cancer cell-immune escape and invasion by downregulating TLR4 expression and inhibiting the TLR4-activated NF-κB pathway." (PMID 20145615, 2010). "The negative association between the TLR4 Gly299 polymorphic allele and a poorer overall survival prognosis has also been reported in head and neck squamous cell carcinoma treated with systemic adjuvant therapies and colon cancer treated with chemotherapy." (PMID 38675738, 2024). "For other tumor types, such as breast or colon cancer, where the overexpression of TLR4 is frequently associated with a negative prognosis, the development of TLR4-inhibiting strategies targeting its co-receptor protein MD-2 could hold therapeutic promise." (PMID 36678520, 2022). "Furthermore, TLR4 signaling seems to be of central importance in the pathogenesis of colitis-associated colon cancer (CAC), as TLR4 was shown to be overexpressed in colonic IECs of UC patients but also in human and murine inflammation-associated colorectal neoplasia." (PMID 34025672, 2021). "Moreover, butyrate was also shown to induce TLR4 expression on colon cancer cells in vitro." (PMID 34025672, 2021). "Taking these findings together, TLR4, which is the most dominant form of TLRs and increased significantly in colon cancer, could serve as a crucial factor for suppression of disialyl Lewisa or sialyl 6- sulfo Lewisx in colon cancer cells." (PMID 32050430, 2020). "To identify whether TLR2 or TLR4 is responsible for the silencing of immunosuppressive Siglec ligands, we analyzed changes in disialyl Lewisa or sialyl 6-sulfo Lewisx glycan expression by knocking down TLR2 or TLR4 by applying specific shRNA for TLR2 or TLR4 in colon cancer cells." (PMID 32050430, 2020).
colon carcinoma (continued). "Moreover, it has been documented that prostate cancer cells are significantly inhibited in terms of tumorigenicity, survival and invasion if TLR4 is down-regulated, while colon cancer death is accelerated, which illustrates that TLR4 plays an important role in carcinogenesis." (PMID 32095158, 2020). "In a colon cancer model HMW-HA binding to TLR4 on cancer cells blocks TLR4 activation by LPS.This raises a question as to whether endogenous HA binding to TLR4 on the basolateral surface of LGR5+ crypt epithelial cells blocks TLR4 activation by LPS." (PMID 33552081, 2020). "Accordingly, mice with toll-like receptor 4 (TLR4, a receptor for bacterial lipopolysaccharide) constitutively activated registered colitis-associated neoplasia more often than WT counterparts, while TLR4 knockout animals developed significantly less colonic tumors when compared to controls." (PMID 31905652, 2019). "Furthermore, we isolated a strain of Fn (F01) from a CRC tissue and examined whether Fn (F01) infection of colon cancer cells activated β-catenin signaling via the TLR4/P-PAK1/P-β-catenin S675 cascade." (PMID 28423670, 2017). "Our data suggest that genetic variation in TLR4 may influence the development of colon cancer." (PMID 26771524, 2016). "Toll-like receptor 4 (TLR4) expression has been investigated in tumor cells or cell lines, including gastric carcinoma, extranodal marginal zone B-cell lymphomas, pituitary epithelial tumor cell lines, hepatocellular carcinoma cells, colon cancer cells and human prostate epithelial PC3 cells." (PMID 24959291, 2014). "Moreover, in the presence of the carcinogen AOM, TLR4 over-expression was sufficient to cause colonic tumors that were not seen in WT mice." (PMID 23691015, 2013). "Intriguingly, high B2M expression showed significantly better prognosis than low B2M expression in colon cancer (p = 0.0021) similarly with CD8A, IFNG and TLR4." (PMID 38557819, 2024). "Makkar found that the combination of HA with CD44 and TLR4 can promote the development of colon cancer, and PEP1 can block the combination of HA with receptors, and inhibit the growth of colon cancer." (PMID 37020597, 2023). "TLR4 and TLR2 enhance metastasis of colon cancers, whereas NOD1 promotes several gastrointestinal malignancies such as colon cancer, as well as head and neck and oral squamous cell carcinoma." (PMID 35130902, 2022). "In CT30 cells of mouse colon cancer or SW480 cells of human colon cancer, butyrate also keeps microbial homeostasis by increasing TLR4 expression as well as phosphorylation of the nuclear factor kappa B (NFKB) and mitogen-activated protein kinase (MAPK)." (PMID 35463305, 2022). "Another recent paper has reported that colon cancer exosomes containing HMGB1 can induce muscle atrophy via the TLR4/nuclear factor-κB (NF-κB) pathway and that serum levels of HMGB1 expression are upregulated in patients with colon cancer cachexia." (PMID 36497194, 2022). "In human colon cancer cell lines HT-29 and SW480, CCK8 assay showed that the cell proliferation was suppressed by the inhibition of TLR4 using TLR4 siRNA." (PMID 34479599, 2021). "In colonic carcinoma cell lines and primary HUVEC, Toll-like receptor 4 (TLR-4), a pattern recognition receptor for LPS, facilitates Stx binding to cells expressing Gb3." (PMID 32456125, 2020). "Membranes-bound pattern recognition receptors (PRRs), including toll-like receptor 4 (TLR4) and 2 (TLR2), have been shown in both in vitro and in vivo studies to enhance metastasis in colon cancers." (PMID 31956962, 2020). "Meanwhile, some investigators showed in another human colon cancer cells SW620, TLR4 activation can trigger the proliferation and migration of cells." (PMID 26760960, 2016). "Among 77 microsatellite stable (MSS) and 78 MSI colon cancers, TLR4 expression strongly correlated with MSI status, with MSI tumors having significantly lower TLR4 expression than MSS comparators (GSE13294).MSI was associated with lower expression of TLR4." (PMID 24887394, 2014).
colon carcinoma (continued). "The expression of TLR4 (a receptor for gram-negative bacterial-derived lipopolysaccharide) is increased in colon cancer, inducing inflammation and promoting colon tumor progression." (PMID 40556945, 2025). "The increase of the expression of TLR4 and the increase of the production of CCL2, COX-2, PGE2, and TNF-α compromise the regeneration of the mucosa, with consequent tissue damage that over time can lead to the development of cancer of the colon." (PMID 35204289, 2022). "In human colon cancer cell lines HT-29, SW480 and Lovo, flow cytometry analysis showed that a significantly high level of apoptosis induced by TNF-related apoptosis-inducing ligand (TRAIL) was attenuated by the typical TLR4 activator LPS." (PMID 34479599, 2021). "In addition to COX-2, several other key proteins involved in the inflammatory environment including TLR4, IFN-γ and PD-L1 were shown to be favorably altered in adjacent normal and colon tumor tissue." (PMID 34926717, 2021). "However, in dMMR/MSH mice, butyrate leads to hyperproliferation, suspends tumor growth and reserves microbial homeostasis by upregulating TLR4 expression and phosphorylation of MAPKs and NF-κΒ in human colon cancer SW480 cells or mouse colon cancer CT26 cells." (PMID 33375686, 2020). "For instance, the majority of colon cancer cells overexpress TLR2, TLR3, and TLR4." (PMID 32012718, 2020). "The importance of F. nucleatum in CRC is further supported by reports that it increases the chemoresistance of colon cancer via modulating autophagy and enhances the proliferation and tumor development of CRC by activating Toll-like receptor 4 (TLR4) signaling." (PMID 32977534, 2020). "TLR4 mRNA tended to increase in human colon cancer cells compared to non-malignant colonic epithelial cells prepared from the same patients." (PMID 32050430, 2020). "Moreover, the inflammatory state of the colon cancer tissue and cells were attributed to primarily activation of the MD2-TLR4 signaling complex, since L6H21 reduced interaction between TLR4 and MD2 in the CT26.WT cells." (PMID 32210720, 2020). "The aim of the study was an evaluation of TLR2 and TLR4 expression on the surface of human colon cancer cells in primary culture with or without autologous peripheral blood mononuclear cells." (PMID 24390484, 2014). "The study was undertaken to evaluate the expression of TLR 2 and TLR4 mRNA in primary in vitro colon cancer cell culture (not cell line)." (PMID 24390484, 2014). "Consistent with the previous results, C16:0 ceramide could not increase colon tumor numbers and volumes in Tlr4–/– mice." (PMID 34914638, 2022). "Research on colon cancer has shown that the level of TIPE2 in colon cancer tissues is significantly upregulated compared to adjacent normal tissues and that TIPE2 participates in the development of colon cancer by binding caspase 8, thereby inhibiting the TLR4 inflammatory pathway." (PMID 33850476, 2021). "Similarly, using a mouse model of colon cancer cell metastasis to lungs, another study showed that MD2 blockage suppressed the metastatic capacity of colon cancer cells in vivo through inhibiting TLR4/MD2 signaling." (PMID 34479599, 2021). "In addition, in colon cancer, andrographolide represses cell proliferation, elevates cell apoptosis, and activates caspase-3/9 in SW620 human colon cancer cells by inhibiting NF-κB, TLR4, MyD88, and MMP-9 signaling activation." (PMID 31242947, 2019). "Therefore, it is most likely that LPS/TLR4/NF-κB signaling in both non-immune (epithelial) and immune (myeloid) cell types contribute to the development of colon cancer." (PMID 27679575, 2016). "In addition, mice lacking TLR4 are protected from developing colon cancer." (PMID 32210720, 2020). "Using S.t-ΔpGlux/pT-ClyA may simultaneously activate TLR4 and NLRP3 signaling pathways, which increase IL-1β expression and enhance inhibition of colon cancer growth without tumor recurrence." (PMID 31754923, 2019).